SPHK1 (sphingosine kinase 1)
Diseases named in the same sentence as SPHK1 in open-access papers (continued):
Sharing a sentence is not in itself a finding about the gene and the disease.
dengue virus infection (3 papers, 2017 to 2020). "In macrophages, a decrease in SphK-1 phosphorylation was reported during leishmaniasis, and SphK-1 inhibition was also reported in dengue virus infection in HEK-293 cells." (PMID 32195246, 2020).
diabetic nephropathy (3 papers, 2017). "In this context, Sphk1 deficiency increases albuminuria and glomerular connective tissue growth factor expression in diabetic nephropathy." (PMID 28282921, 2017). "Accumulating evidence suggests that SphK1 is closely associated with inflammation, cardiovascular system and immune system, affecting diabetic nephropathy, angiogenesis, vascular maturation, smooth muscle cell proliferation and immune inflammatory regulation." (PMID 29179493, 2017). "Dania found that inhibiting the formation of S1P by knockout SphK1 reduces tubulointerstitial renal inflammation and fibrosis in diabetic nephropathy." (PMID 29108256, 2017). "Ren found that SphK1 expression increased in the podocytes of kidney sections of patients with diabetic nephropathy and exacerbation of disease was detected by increased albuminuria and CTGF expression in SphK1 deficient mice." (PMID 29108256, 2017).
lymphoma (3 papers, 2016 to 2023). A malignant (clonal) proliferation of B- lymphocytes or T- lymphocytes which involves the lymph nodes, bone marrow and/or extranodal sites. "Using a web-based database, Gene Expression Omnibus (GEO), the high throughput gene expression was profiled for SPHK1 and SPHK2 in the lymphomas (DLBCL, FL, and PTCL) and the respective normal controls." (PMID 36600310, 2023).
non-Hodgkin lymphoma (3 papers, 2013 to 2021). Distinct from Hodgkin lymphoma both morphologically and biologically, non-Hodgkin lymphoma (NHL) is characterized by the absence of Reed-Sternberg cells, can occur at any age, and usually presents as a localized or generalized lymphadenopathy associated with fever and weight loss. "Tissues from patients with non-Hodgkin’s lymphoma presented higher SphK1 protein and mRNA levels than tissues from patients with reactive lymphoid hyperplasia." (PMID 26824863, 2016). "Accumulating data show increased levels and activity of Sphingosine kinase 1, one of the biosynthetic enzymes of S1P, in cancers of the stomach, lung, brain, colon, kidney, breast and non-Hodgkin’s lymphoma." (PMID 24276423, 2013).
ovarian tumor (3 papers, 2013 to 2022). "Thus, our data show that SPHK1, associated with EVs, has a critical role in ovarian tumor progression." (PMID 35289120, 2022). "Transcript levels of ACTA2 (the gene encoding αSMA) and FAP were significantly higher in SPHK1-High tumors than in SPHK1-Low tumors in both the AOCS and TCGA datasets, suggesting that SPHK1 could be associated with an increased abundance of CAFs in ovarian tumors." (PMID 26716409, 2016). "Collectively, our data demonstrate that SPHK1‐packaged EVs mediates extracellular modulation of S1P signaling, promoting the growth of ovarian tumors via immune suppression." (PMID 35289120, 2022). "Additionally, we injected parental ID8 cells, RAB27a−/− ID8 cells, SPHK1−/− ID8 cells, and SPHK1 ectopic expressing (EE) ID8 cells in the ovary of C57BL/6 mice to know the direct association of SPHK1 with the ovarian tumor growth." (PMID 35289120, 2022).
pancreatic adenocarcinoma (3 papers, 2021 to 2022). "Our analysis suggests plausible role for SPHK1 in development of pancreatic adenocarcinoma in long standing CP patients." (PMID 35854233, 2022).
pancreatic ductal adenocarcinoma (3 papers, 2022 to 2025). An infiltrating adenocarcinoma that arises from the epithelial cells of the pancreas. "SPHK1 was earlier reported to be upregulated in pancreatic ductal adenocarcinoma demonstrating resistance to gemcitabine, its regulation of angiogenesis and miRNA 506/SPHK1 axis as a therapeutic target." (PMID 35854233, 2022). "In pancreatic ductal adenocarcinoma patient samples, SPHK1 was shown to correlate with enhanced stemness as measured using gene-expression–based metrics, and siRNA mediated silencing of SPHK1 dramatically reduced colony formation, consistent with SPHK1 promoting CSC function." (PMID 41253780, 2025).
Parkinson disease (3 papers, 2017 to 2023). A progressive degenerative disorder of the central nervous system characterized by loss of dopamine producing neurons in the substantia nigra and the presence of Lewy bodies in the substantia nigra and locus coeruleus. "The most significant SPHK1 SNP rs2247856 was reported recently as a significantly associated variant with Parkinson’s disease in both genders." (PMID 36817779, 2023). "For example, inhibiting sphingosine kinase decreases dopaminergic neuron viability by increasing ROS, and Sphk1 expression is decreased in a Parkinson's disease model." (PMID 28983319, 2017).
renal cell carcinoma (3 papers, 2021 to 2022). "SPHK1 upregulation in renal cell carcinoma may promote cancer progression, and its silencing may suppress cell proliferation via reduced HIF-2α expression." (PMID 33679977, 2021). "Previous studies suggests that SPHK1 regulates AKT phosphorylation and silencing of SPHK1 results in impaired AKT phosphorylation in renal cell carcinoma." (PMID 35127873, 2021). "We previously identified SphK1/S1P signaling as a new modulator of HIF-1α and HIF-2α activities under hypoxia in a wide array of cancer cell models (prostate, glioma, breast, lung and renal cell carcinoma) both in vitro and in vivo." (PMID 35158767, 2022).
sickle cell disease (3 papers, 2021 to 2024). Sickle cell anemias are chronic hemolytic diseases that may induce three types of acute accidents: severe anemia, severe bacterial infections, and ischemic vasoocclusive accidents (VOA) caused by sickle-shaped red blood cells obstructing small blood vessels and capillaries. "In prior work, we have shown that RBCs upregulate S1P synthesis via Sphk1 to counteract hypoxia at high altitude or in sickle cell disease." (PMID 33351786, 2021). "Moreover, in sickle cell disease, the binding of adenosine to ADORA2B activates SPHK1, thereby increasing S1P production." (PMID 38426208, 2024).
Thrombocytopenia (3 papers, 2020 to 2025). A reduction in the number of circulating thrombocytes. "Taken together, we present the experimental proof of decreased S1P levels during malaria infection associated with thrombocytopenia and chronic malaria because of altered SphK-1 activity." (PMID 32195246, 2020). "Investigations of the development of thrombocytopenia based on blood cell analysis contradicted the development of this part of the HUS triad in WT, SphK1−/−, and SphK2−/− mice with experimental HUS in this study at first glance." (PMID 39062926, 2024). "Based on our findings, we propose a regulation of host SphK-1 as a factor for reduced S1P levels during parasite infection, which might lead to attenuated thrombopoiesis via S1P1 and/or S1P4 signaling pathways, thereby leading to thrombocytopenia." (PMID 32195246, 2020).
Anxiety (2 papers, 2021 to 2022). Intense feelings of nervousness, tension, or panic often arise in response to interpersonal stresses. "A previous study has reported that Kpna1 KO mice show decreased anxiety-like behavior (in EPM and OFT), which was attenuated by either administration of a Sphk1 inhibitor PF-543, or rescue of Kpna1 in the ventral hippocampus." (PMID 34767585, 2021).
astrocytoma (2 papers, 2012 to 2014). "Furthermore, SphK1 mRNA was significantly elevated in various tumor tissues (brain, breast, lung, ovary, stomach, colon), and a higher expression of SphK1 in human astrocytoma tissue correlated with a shorter patient survival time." (PMID 23028939, 2012).
brain tumor (2 papers, 2022 to 2023). "Recent work in brain tumors has focused on inhibiting sphingosine kinase 1 to decrease the production of S1P, thus preserving the pro-apoptotic capability of ceramides." (PMID 35741006, 2022). "In this context, the acid ceramidase (acid CDase) and SphK1, which drive rheostat from ceramide to S1P, were reported to be higher in GBM tissues compared to normal brain, with acid CDase associated also to neural stem cell-like brain tumor-initiating cells (BTIC) markers." (PMID 38203299, 2023).
cardiac insufficiency (2 papers, 2022 to 2023). "Apigenin, an anti-inflammatory dietary flavonoid, mitigated LPS-induced heart failure by inhibiting SphK1 activity." (PMID 36361636, 2022).
chronic hepatitis C (2 papers, 2020 to 2023). "M2c macrophages polarized from patients with chronic hepatitis C, expressed lower levels of SPHK1 than those from healthy controls." (PMID 36674922, 2023).
chronic pancreatitis (2 papers, 2022 to 2023). A chronic inflammatory process causing damage and fibrosis of the pancreatic parenchyma. "Another study also demonstrated that SPHK1 upregulation may play a potential role in early neoplastic transformation of inflammatory lesions in long-standing chronic pancreatitis patients." (PMID 37999228, 2023).
cognitive deficits (2 papers, 2018 to 2020). "Overall, the data presented here show that decreased SphK1 levels in AD neurons worsen microglia function, resulting in failure of resolution and exacerbation of AD pathology, namely Aβ plaque deposition and cognitive impairment." (PMID 29662056, 2018). "MiR-125b-1 induced tau hyperphosphorylation and cognitive deficits in AD, may be involved in the regulation of inflammatory factors and oxidative stress by SphK1." (PMID 33013313, 2020).
colon adenocarcinoma (2 papers, 2022 to 2025). "Colon adenocarcinoma (COAD) stands out as a tumor characterized by particularly high levels of CXCL12 and S1P through SPHK1 activation." (PMID 40155684, 2025).
endometrial carcinoma (2 papers, 2022 to 2024). A malignant tumor arising from the epithelium that lines the cavity of the uterine body. "High levels of S1P are found in endometrial carcinoma, resulting from both the activation of SphK1 and the abundance of its substrate, sphingosine, and there is evidence that SphK1 inhibitors reduce cell proliferation and tumor growth both in vitro and in vivo." (PMID 36362323, 2022).
endometriosis (2 papers, 2022). The growth of functional endometrial tissue in anatomic sites outside the uterine body. "In fact, to achieve their scope, the authors used a recognized mouse model of endometriosis and by the use of SphK1-5C, the specific SphK1 inhibitor, the growth and vascularization of endometriotic lesions was prevented." (PMID 36362323, 2022). "However, gene expression involved in ceramide synthesis (SPHK1, ASAH1, and SGPP1) and autophagy (BECN1, LAMP, and PC3) were significantly lower in MGCs with endometriosis, whereas CERS1 and UGCG expression increased." (PMID 35992117, 2022).
erythroleukemia (2 papers, 2022 to 2025). Acute erythroid leukemia characterised by the presence of at least 50% erythroid precursors and at least 20% myeloblasts in the bone marrow. "One of the enzymes recently linked to the insurgence of erythroleukemia was SPHK1." (PMID 36361536, 2022). "SPHK1 is specifically expressed in the erythroid lineage and SPHK1 overexpression has been identified as an oncogenic event in the progression of erythroleukemia." (PMID 40221405, 2025). "In a model of erythroleukemia induced by overexpression of SPI1/PU.1 in proerythroblasts, as well as in Spi-1 overexpressing transgenic mice, Sphk1 was found to be transcriptionally upregulated." (PMID 36361536, 2022).
fibrosarcoma (2 papers, 2019 to 2020). A malignant mesenchymal fibroblastic neoplasm affecting the soft tissue and bone. "One of these possible substrates inside the cells is PA, which activates Sos (son of sevenless), Raf (rapidly accelerated fibrosarcoma), MAPK, mTOR (mammalian target of rapamycin), AKT (Ak strain transforming), and SPHK1." (PMID 32887262, 2020). "The overexpression of wild-type SPHK1, but not the inactive mutant, transforms NIH3T3 cells into fibrosarcoma." (PMID 32887262, 2020).
gastric adenocarcinoma (2 papers, 2015 to 2026). "Many previous investigations have identified SPHK1 as overexpressed in several cancer types including gastric adenocarcinoma and associated with increased stage and poor survival." (PMID 26493335, 2015). "Our experiments with gastric adenocarcinoma cell lines suggest that safingol, a SPHK1 inhibitor, has cytotoxic effects as a single agent as well as acting synergistically with cisplatin." (PMID 26493335, 2015). "We investigated the ability of safingol, an inhibitor of SPHK1, to reverse cisplatin resistance in gastric adenocarcinoma." (PMID 26493335, 2015). "In addition SPHK1 activity and levels of S1P have been demonstrated to be involved in resistance to cytotoxic and targeted agents in a variety of cancer types, although not oesophageal or gastric adenocarcinoma drug resistance." (PMID 26493335, 2015).
Glucose intolerance (2 papers, 2014 to 2020). Glucose intolerance (GI) can be defined as dysglycemia that comprises both prediabetes and diabetes. "In addition, one study discovered that HFD-fed SphK1 KO mice displayed a reduction in β cell size, number, and mass associated with increased β cell apoptosis compared to WT HFD-fed mice, which all favor the installation of glucose intolerance." (PMID 32668665, 2020).
HCMV infection (2 papers, 2019 to 2021). "Machesky and colleagues noted increased sphingosine kinase 1 (SphK1) activity and increases in dihydrosphingosine 1-phosphate (dhS1P) and ceramide levels in response to HCMV infection." (PMID 34073578, 2021). "Human cytomegalovirus (HCMV) infection increased SphK1 enzymatic activity and the resultant S1P levels, and the inhibition or downregulation of SphK1 interfered with HCMV replication." (PMID 31783527, 2019).
hemorrhage (2 papers, 2016 to 2024). Loss of blood from the vascular compartment to the exterior or into nonvascular body space as a result of rupture or severance of the blood vessels. "A prior study has reported that following ICH, Sphk1 is upregulated in neuronal cells, where it contributes to neuronal injury through inducing ferroptosis and thus promotes secondary brain injury post-hemorrhage." (PMID 39715736, 2024).
Hyperglycemia (2 papers, 2022 to 2023). An increased concentration of glucose in the blood. "Similarly, hyperglycemia/AGEs activated SphK1/S1P, leading to glomerular and MC proliferation via TGF-β." (PMID 35409370, 2022). "In addition, hyperglycemia stimulated TGF-β-induced FN expression in HK-2 cells, while the inhibition of SphK1 prevented these events by inhibiting ERK/AP-1/NF-κB." (PMID 35409370, 2022).
infarction (2 papers, 2017 to 2023). A localised pathological necrosis of tissue resulting from obstruction of the blood supply usually by a thrombus, an embolus, or vascular torsion. "ATF3 and SPHK1 downregulation narrowed the infarction area and attenuated myocardial fibrosis in mice, along with reduced inflammation in the serum and ER stress in the myocardium." (PMID 37773702, 2023).
ischemic heart disease (2 papers, 2021 to 2025). "However, the up-regulated SphK1 improves the other diseases (such as ischemic heart disease and HD), which is characterized by the decrease of SphK1 expression or activity in the disease state." (PMID 34737701, 2021).
kidney cancer (2 papers, 2016 to 2017). Primary or metastatic malignant neoplasm involving the kidney. "In summary, the present report demonstrates that the SphK1/S1P signaling pathway is a potent regulator of HIF-2 in human cancer notably in ccRCC, the most common form of kidney cancer." (PMID 26974204, 2016).
kidney injury (2 papers, 2017 to 2022). Trauma to the kidney. "In contrast to the survival effects of SphK1, SphK2 promotes apoptosis/cell death in various types of oxidant-induced kidney injury." (PMID 35409370, 2022). "Taken together, these lines of evidence suggest that SphK1 promotes survival, while SphK2 has the opposite effect in oxidant-induced kidney injury." (PMID 35409370, 2022). "Further studies are needed to determine whether SphK1 and SphK2 differentially regulate cell proliferation in oxidant-induced kidney injury." (PMID 35409370, 2022). "It was indicated that AGEs could elevate the expression and activity of SphK1, SphK1 knockout could reverse AGEs-induced kidney injury in mice." (PMID 29108256, 2017). "Taken together, these data suggest that SphK1 prevents inflammation via HIF-1α and HSP27 and by inhibiting proinflammatory cytokines in oxidant-induced kidney injury." (PMID 35409370, 2022). "Taken together, these data suggest that HIF-α activates SphK1 activity and SphK1/S1P1R-induced HSP27 protects against apoptosis in oxidant-induced kidney injury." (PMID 35409370, 2022). "Taken together, these data suggest that SphK1 protects against apoptosis by activating ERK/PI3K/Akt/PKB and growth factors such as IGF and VEGF which share the same survival signaling pathways in oxidant-induced kidney injury." (PMID 35409370, 2022). "Thus, SphK1 and ERK activate each other and function as anti-apoptotic in oxidant-induced kidney injury." (PMID 35409370, 2022).
large granular lymphocyte leukemia (2 papers, 2022 to 2023). "S1P levels are high in the peripheral blood of NK-LGL leukemia patients, and this has been attributed to overexpression of SPHK1 in PBMCs of these patients." (PMID 36361536, 2022). "Hence it is possible that the higher expression of both AC and SPHK1 in LGL leukemia cells is responsible for the larger production of S1P which in turn provides a proliferative/survival advantage." (PMID 36361536, 2022).
lymphangioleiomyomatosis (2 papers, 2023 to 2025). A multifocal neoplasm with perivascular epithelioid cell differentiation affecting almost exclusively females of child-bearing age. "In lymphangioleiomyomatosis, activated SphK1/S1P/S1PR3 signaling promotes mTORC1 activation and autophagy suppression, reducing tumor cell survival, migration, and invasion." (PMID 40906080, 2025). "SphK1/S1P/S1PR3 signaling is activated in Lymphangioleiomyomatosis (LAM), leading to mTORC1 activation and autophagy inhibition." (PMID 37852968, 2023).
lymphopenia (2 papers, 2011 to 2017). Reduction in the number of lymphocytes. "While many studies including the results presented here strongly support a role for SphK1 in cellular functions such motility and collagen production, a recent report suggests that SphK2 deficiency contributes to reduced S1P accumulation in lymphoid tissues and attenuated T and B cell lymphopenia." (PMID 21304987, 2011).
metabolic syndrome (2 papers, 2020 to 2023). A cluster of metabolic risk factors for CARDIOVASCULAR DISEASES and TYPE 2 DIABETES MELLITUS. "Sphingosine kinase 1 (Sphk1) is a critical enzyme in sphingolipid metabolism that has been implicated in various metabolic syndromes." (PMID 33208918, 2020).
metastasis (2 papers, 2017 to 2023). The spread or migration of cancer cells from one part of the body (where they first appeared) to another. "Increased expression of SPHK1 is associated with lymph node and liver metastasis, and advancement in the TNM stage." (PMID 36902343, 2023).
metastatic cancers (2 papers, 2014 to 2016). A carcinoma which has spread from the original site of growth to another anatomic site. "Taken together, S1P secretion with an increase the SphK1 expression in stiff substrate is characteristic of aggressive metastatic cancer cells." (PMID 26877098, 2016). "We also showed that MDA-MB-231 and H1299, the aggressive metastatic cancers, increased SphK1 expression and adhesive activity in the stiff substrate." (PMID 26877098, 2016). "We also found that upregulation of SphK1 expression in the stiff substrate is dominant in metastatic cancer cells but not in primary cancer cells." (PMID 26877098, 2016).